FGFR3 (fibroblast growth factor receptor 3)
Diseases named in the same sentence as FGFR3 in open-access papers (continued):
Sharing a sentence is not in itself a finding about the gene and the disease.
melanoma (29 papers, 2013 to 2025). A malignant, usually aggressive tumor composed of atypical, neoplastic melanocytes. "FGFR3 may be an excellent biomarker for evaluating the risk of metastasis in melanoma patients." (PMID 31619201, 2019). "It was also documented that FGFR3 promotes the growth, colony formation, migration, and invasion abilities of melanoma A375 cells." (PMID 38473753, 2024). "The cross-suppression of both AREG and EREG has also been reported to lead to the emergence of CTX resistance, which is related to the loss of cell addiction to EGFR, compensated by the hyperactivation and addiction to FGFR3 in melanoma." (PMID 36899869, 2023). "Subgroup analyses showed that the mutation frequencies of melanoma regarding FGFR1, FGFR2, FGFR3 and FGFR4 ranked 1st, 2nd, 2nd, and 2nd across all cancers, respectively." (PMID 36426352, 2022). "The reactivation of ERK seems to be crucial for the resistance to BRAF inhibitors in melanoma cells with BRAF-V600E mutations, and one of the mediators is FGFR3." (PMID 34830951, 2021). "High levels of IGF-1 and FGFR-3 have been found in biopsies of melanoma patients treated with BRAF inhibitors in monotherapy or in combination with MEK inhibitors and IGF-1, and its receptor (IGF-1R) are associated with resistance to MAPK inhibitors." (PMID 33036192, 2020). "The FGFR3 knockdown triggered a reduction in the size of tumors in mice xenografts, which further confirmed that FGFR3 is involved in the growth of melanoma." (PMID 31619201, 2019). "The protein expression of FGFR3 in the malignant melanoma tissues was correlated with the Breslow thickness and lymph node metastasis (p < 0.05)." (PMID 31619201, 2019). "FGFR3 is highly expressed in malignant melanoma tissues and correlates with Breslow thickness and lymph node metastasis." (PMID 31619201, 2019). "The knockdown of FGFR3 also decreased the cell migration and invasion abilities of the melanoma cells." (PMID 31619201, 2019). "The mRNA expression level of FGFR3 was significantly higher in melanoma tissues than the surrounding normal healthy tissues." (PMID 31619201, 2019). "E-cadherin expression increased in the melanoma cells, while the expression of N-cadherin and vimentin decreased after the knockdown of FGFR3 in A357 cells." (PMID 31619201, 2019). "FGFR3 promotes melanoma growth, metastasis, and EMT behaviors, likely by affecting the phosphorylation levels of ERK, AKT, and EGFR." (PMID 31619201, 2019). "FGFR3 regulates malignant melanoma growth, metastasis, and EMT behaviors by influencing the phosphorylation levels of ERK, AKT, and EGFR." (PMID 31619201, 2019). "When FGFR3 was overexpressed, colony formation and cell proliferation increased, which was in combination with decreased apoptosis of caspase-3 activity in the melanoma cells in vitro." (PMID 31619201, 2019). "Knockdown of FGFR3 significantly (p < 0.05) increased the apoptosis rate, while FGFR3 overexpression significantly decreased the apoptosis rate of melanoma cells in vitro." (PMID 31619201, 2019). "FGFR3 activation has been proposed as a mechanism of acquired resistance to vemurafenib in BRAFV600E melanomas and to cetuximab in KRAS wild type SCC." (PMID 31167513, 2019). "Together, these results indicate that FGFR3 facilitates the metastasis of melanoma through ERK, AKT, and EGFR-activated EMT pathways." (PMID 31619201, 2019). "In this study, we investigated the role of FGFR3 in the growth and metastasis of melanoma using FGFR3 knockdown and overexpression strategies in vitro and in vivo." (PMID 31619201, 2019). "In this study, FGFR3 expression was higher in melanoma tissues than the surrounding healthy tissues." (PMID 31619201, 2019). "Further, in line with our observation that TAB cells induce drug resistance via IGF-1 and activation of the FGFR-3 receptor in tumor cells, drug resistance of melanoma cells was dependent on the presence of FGFR-3." (PMID 28928360, 2017).
melanoma (continued). "Several studies have shown that over-expression of EGFR, FGFR3, PDGFRβ, CRAF, and NRAS in melanoma have been associated with BRAFi resistance." (PMID 27448964, 2016). "Notably, FGFR intergenic-breakpoint fusions—novel potentially druggable alterations—were less common in our cohort (4.39%, 5/114) than in the MSKCC cohort (14.38%, 22/153), and included a newly identified FGFR3 intergenic-breakpoint fusion in melanoma." (PMID 41092072, 2025). "Similarly, the level of FGFR3 was significantly higher in melanoma than in the surrounding healthy tissues." (PMID 38473753, 2024). "Fibroblast growth factor receptor 3 (FGFR3) is among the receptor tyrosine kinases which may be activated via autocrine circuits in melanoma." (PMID 37251404, 2023). "Mutations found in melanomas on the dorsal hand and foot were reported to be similar to those in melanomas at other sites of intermittently sun-damaged skin, whereas subungual and interdigital melanomas (n = 13) exhibited diverse mutations in PIK3CA, STK11, EGFR, FGFR3, and PTPN11." (PMID 36983205, 2023). "Additionally, FGFR2 promotes melanoma metastasis and recently, the implication of FGFR3 in melanoma growth, metastasis, and EMT behaviors was elucidated, through modulation of phosphorylation levels of ERK, AKT, and EGFR." (PMID 33918490, 2021). "Fibroblast growth factor receptor 3 (FGFR3) may promote melanoma growth, metastasis, and EMT behavior by influencing the phosphorylation levels of ERK, AKT, and EGFR." (PMID 33240619, 2020). "FGFR3 promoted melanoma cell proliferation, colony formation, migration, and invasion in vitro." (PMID 31619201, 2019). "In this study, we found that FGFR3 was highly expressed in melanoma tissues." (PMID 31619201, 2019). "FGFR3 expression was correlated with the Breslow thickness of melanoma, suggesting that FGFR3 may promote the growth of melanoma." (PMID 31619201, 2019). "FGFR3 may also promote the growth of melanoma through the EGFR signaling pathway by stimulating the phosphorylation of EGFR." (PMID 31619201, 2019). "The mRNA expression of FGFR3 was higher in melanoma tissues than normal healthy tissues." (PMID 31619201, 2019). "In this study, we aimed to uncover the role of FGFR3 in the growth and metastasis of melanoma." (PMID 31619201, 2019). "Inhibition of the FGFR3/RAS axis could restore the sensitivity of resistant melanoma cells to vemurafenib." (PMID 31167513, 2019). "FGFR3 knockdown and overexpression strategies were employed to investigate the effects of FGFR3 on colony formation, cell apoptosis, proliferation, migration, and in vitro invasion, along with the growth and metastasis of melanoma in a xenografts mouse model." (PMID 31619201, 2019). "Together, all these results suggest that FGFR3 promotes the metastasis of melanoma." (PMID 31619201, 2019). "FGF-2 produced by melanoma cells is a natural ligand for FGFR-3." (PMID 28928360, 2017). "Together, these data support a FGF-2-induced conversion of B cells into a tumor-supportive phenotype which, with IGF-1 as critical key growth factor, reciprocally provides sustained pro-inflammatory and pro-tumorigenic signals to melanoma cells leading to activation of FGFR-3." (PMID 28928360, 2017). "In addition, FGFR3 promoted the growth and metastasis of melanoma cells in vivo." (PMID 31619201, 2019). "Induction of FGF-2 and FGFR-3 expressions in melanoma cells could be detected from 48 h on." (PMID 28928360, 2017). "Melanoma secretes fibroblast growth factor 2 (FGF2), which actives B cells through its binding to fibroblast growth factor receptor 3 (FGFR-3) and promotes the release of insulin-like growth factor 1 (IGF-1)." (PMID 33036192, 2020). "B-cell-derived IGF-1 is critical for resistance of melanomas to BRAF and MEK inhibitors due to emergence of heterogeneous subpopulations and activation of FGFR-3." (PMID 28928360, 2017).
melanoma (continued). "The RAS-driven signal transduction can be also stimulated by activation of the fibroblast growth factor receptor 3 (FGFR3), again conferring resistance to vemurafenib in BRAFV600E melanoma cells." (PMID 26322273, 2015). "In the “Other tumors group” four rearrangements involving BRAF gene were detected (three melanoma: BRAF::CNNM2, BRAF::ERC1, BRAF::MAD1L1 and one pancreatic adenocarcinoma BRAF::SND1), but also one ETV6::NTRK3 (colorectal cancer) and one FGFR3::TACC3 (urothelial cancer)." (PMID 37708140, 2023). "The expression of IGF1 mediated upregulation of FGFR3 and STAT3 in both TAB and melanoma cells." (PMID 34830951, 2021). "Interestingly, the deactivation of FGFR3 was also able to overcome the resistance indicting the correlation between IGF1 and FGFR3 in the chemoresistance in human melanoma cells." (PMID 34830951, 2021). "In addition to FGFR3, FGFR4 expression has been correlated with the metastasis of melanoma in patients." (PMID 31619201, 2019). "Analysis of VEGFR1, VEGFR2, FGFR1, FGFR3 and VE-Cadherin expression levels in B16F0 melanoma cells, and tumors isolated from control and DCKO mice showed ~30% reduced levels of VEGFR2 (but not VEGFR1) in DCKO mice compared to DFF control littermates, consistent with Vegfr2 haploinsufficiency." (PMID 30283071, 2018). "The effect of TAB cells on melanoma heterogeneity and therapy resistance could be reversed by IGF-1 neutralization or FGFR-3 knockdown." (PMID 28928360, 2017). "We observed an increased expression of IGF-1 in melanoma lesions from patients treated with either BRAFi alone or BRAFi/MEKi combination therapies and increased IGF-1 correlated well with higher expression of FGFR-3 and CD20." (PMID 28928360, 2017). "In particular, our custom panel covers all regions of MELP Panel (MAYO Clinic Laboratories), while it does not include AKT3 (exon 5 and 6) and FGFR3 (exon 7, 9, and 14) genes included in the Sentosa® SQ Melanoma Panel (Vela Diagnostics)." (PMID 33317587, 2020). "In A375 human malignant melanoma cells, arbutin at high concentration (1 mM) up-regulated 88 genes and down-regulated 236 genes, including genes (AKT1, CLECSF7, FGFR3, and LRP6) controlling cell cycle progression, hence, suggesting that it may act similarly on neutrophils." (PMID 32731392, 2020). "However, the role of FGFR3 in melanoma has not been elucidated." (PMID 31619201, 2019).
cervical carcinoma (28 papers, 2002 to 2026). A carcinoma arising from either the exocervical squamous epithelium or the endocervical glandular epithelium. "The FGFR3 p.S249C mutation leads to poor patient results mainly in cases of cervical cancer and OPSCC with HPV." (PMID 41487403, 2026). "The genetic contribution of FGFR3 to cervical cancer risk was further investigated in the Chinese population." (PMID 30616520, 2019). "The association of the high expression of FGFR3 with better survival in cervical cancer was also confirmed by a recent study." (PMID 30445744, 2018). "Our study suggested that somatic mutations in EGFR, FGFR2, and FGFR3 are rare in cervical cancers; this result was similar to the findings of previous studies." (PMID 25669975, 2015). "When all study results are grouped, the overall FGFR3 mutation rate in cervical carcinoma worldwide is 1.7%." (PMID 15869706, 2005). "We previously reported specific FGFR3 missense mutations in 3 out of 12 invasive cervical carcinomas." (PMID 15869706, 2005). "Studies about FGFR3 mutation in cervical cancer reported various rates of mutation, ranging from 0% to 25%." (PMID 15869706, 2005). "Genes with higher expression in FGFR3 mutated cervical carcinomas compared to wildtype FGFR3 cervical carcinomas." (PMID 15869706, 2005). "We showed that FGFR3 mutated tumors are more likely to be associated with a non-HPV16/18 type and that patients with mutated FGFR3 cervical carcinoma are older than patients with wildtype FGFR3 tumor." (PMID 15869706, 2005). "We compared expression profiles of 3 FGFR3 mutated cervical carcinomas with the expression profiles of 17 wildtype FGFR3 cervical carcinomas, using SAM analysis as described in the methods section." (PMID 15869706, 2005). "Including this work, 6 studies analyzed a total of 349 cervical cancer samples and found 6 FGFR3 mutations (1.7%)." (PMID 15869706, 2005). "To extend our previous report of FGFR3 mutation in 3 of 12 cervical carcinomas, we selected 63 additional cases for a total of 75 screened DNAs." (PMID 15869706, 2005). "Here we showed that FGFR3 is mutated in 5% (4 of 75 cases) of invasive cervical carcinomas from a French cohort of patients (including 3 cases previously reported)." (PMID 15869706, 2005). "FGFR3 inhibitors may thus represent a potential therapeutic method for cervical cancer patients with FGFR3 mutations." (PMID 36333792, 2022). "Mutations of FGFR3 were reported in 3 out of 12 primary French cervical carcinomas." (PMID 30616520, 2019). "Taken together, our study showed FGFR3 mutation in 4 of 75 invasive cervical cancer (5%)." (PMID 15869706, 2005). "Hence, we searched for all published papers on FGFR3 mutations in cervical cancer, by interrogating Medline with the terms "cervical cancer" and "FGFR3"." (PMID 15869706, 2005). "Total number of cervical carcinoma cases screened for FGFR3 mutation, as of august 2004." (PMID 15869706, 2005). "In this study, we performed RNA sequencing of 116 cervical cancer samples and detected four cases with fusion genes involving FGFR3 or ROS1 as potential therapeutic targets." (PMID 37537783, 2023). "FGFR3 fusions were characteristic of bladder/urinary tract cancer (1.8%), central nervous system/brain tumors (1.2%), cervical cancer (0.6%), kidney cancer (0.4%), and esophagogastric/stomach cancer (0.4%)." (PMID 37537783, 2023).
cervical carcinoma (continued). "We also evaluated the frequency of patients with FGFR3 fusion‐positive cervical cancer in the C‐CAT database." (PMID 37537783, 2023). "FGFR3 fusion cases were characteristic of bladder/urinary tract cancer and cervical cancer, with a high prevalence of 1.7% and 1.5%, respectively." (PMID 37537783, 2023). "A search of publicly available data from cBioPortal (21,789 cases) and the Center for Cancer Genomics and Advanced Therapeutics (32,608 cases) showed that the FGFR3 fusion is present in 1.5% and 0.6% of patients with cervical cancer, respectively." (PMID 37537783, 2023). "We transfected a “kinase-dead mutant” FGFR3-TACC3 fusion transcript (“FGFR3-TACC3 KD fusion”) into Ect1/E6E7, SiHa, and ME180 to investigate the significance of FGFR3 kinase activity in FGFR3-TACC3 fusion-positive cervical cancer." (PMID 29358619, 2018). "Considering that the frequency of FGFR3 fusion is lower in advanced cases, the prognosis of patients with cervical cancer with this fusion may be better." (PMID 37537783, 2023). "Other examples include miR-133b direct downregulation of FGFR1 expression and RAS-MAPK/PI3K-AKT signaling in osteosarcoma cells, miR-889-3p decreasing FGFR2 expression in cervical cancer and miR-24-3p downregulation of FGFR3 expression in multiple myeloma (MM) and lung adenocarcinoma." (PMID 34068954, 2021). "No studies have previously reported a correlation between FGFR3 polymorphisms within the Chinese population and a genetic predisposition to cervical cancer." (PMID 30616520, 2019). "Although there is the heterogeneity of HPV-related tumors at different anatomical sites, alteration of FGFR2 and FGFR3 could also be worthwhile to study in cervical cancers." (PMID 27154171, 2016). "The FGFR3 is a tyrosine kinase receptor, the constitutive activation of which is involved in skeletal malformations and drives tumour cell growth in bladder and cervix cancer." (PMID 20234367, 2010). "Since its first description, the role of FGFR3 mutation in cervical carcinoma has been debated when some studies reported an absence of mutation in a total of nearly 200 cases analyzed." (PMID 15869706, 2005). "Also, data describing the relationships between FGFR3 polymorphisms and a genetic predisposition to cervical cancer have not been reported in China." (PMID 30616520, 2019). "Of 974 patients with advanced cervical cancer in the C‐CAT database, six FGFR3 fusion‐positive cases were identified." (PMID 37537783, 2023). "The aberrant expression of many mRNAs, including FGFR3, CTGF, TP63, IL36G, ADH7, SPINK5, and so on, have also been identified in cervical cancer." (PMID 32123519, 2020). "In the present study, we investigated the prognostic significance of FGFR1, FGFR2, FGFR3, and FGFR4 expression in a large cohort of cervical cancer patients." (PMID 27154171, 2016). "In conclusion, the present study investigated the immunohistochemical expression of FGFR1, FGFR2, FGFR3, and FGFR4 in a large number of cervical cancer patients." (PMID 27154171, 2016). "Cox regression analysis confirmed that FGFR2, FGFR3, and FGFR4 expression was an important prognostic indicator in cervical cancer." (PMID 27154171, 2016). "TATs highly expressed in cervical cancer include CEACAM5, CD71, CD138, FGFR3, LYPD3, CEACAM6, etc.; VEGF is also highly expressed in ovarian cancer; CD71 and CD138 are highly expressed in endometrial cancer; the TATs highly expressed in uterine sarcoma include B7-H3, DLK1, and EFNA4." (PMID 40046734, 2025). "However, the frequency of FGFR3 fusion in the C‐CAT database, which consists of only advanced cervical cancer cases, is 0.62%." (PMID 37537783, 2023). "The frequency of the FGFR3 fusion gene was higher in cervical cancer than in other cancers, regardless of ethnicity." (PMID 37537783, 2023). "Furthermore, we demonstrate for the first time that elevated expression of FGFR2, FGFR3, or FGFR4 predict favorable survival in cervical cancer patients." (PMID 27154171, 2016).
cervical carcinoma (continued). "Thus, the aim of this study is to investigate the clinical significance of FGFR1, FGFR2, FGFR3 and FGFR4 expression in a well-defined cohort of cervical cancers, using immunohistochemistry and quantitative digital image analysis." (PMID 27154171, 2016). "FGFR3 fusion was detected in cervical cancer regardless of ethnicity and histology." (PMID 37537783, 2023). "Additionally, the FGFR3 gene, which has no known role in cervical cancer, was chosen for subsequent analysis." (PMID 30616520, 2019). "FGFR1, FGFR2, FGFR3, and FGFR4 expression was determined by immunohistochemistry in conjunction with quantitative digital image analysis of 336 formalin-fixed, paraffin-embedded cervical cancer tissues and 61 normal cervical tissues, as well as NCI60 cell microarray." (PMID 27154171, 2016).